IL18 (interleukin 18)
Diseases named in the same sentence as IL18 in open-access papers (continued):
Sharing a sentence is not in itself a finding about the gene and the disease.
acute kidney injury (continued). "This study analyzed the outcomes of coronary care unit (CCU) patients and evaluated several biomarkers of acute kidney injury (AKI), including neutrophil gelatinase-associated lipocalin (NGAL), interleukin-18 (IL-18) and cystatin C (CysC) on the first day of CCU admission." (PMID 22384218, 2012). "Notably, cancer-induced hyperuricemia, hyperkaliemia, acute kidney injury (AKI), anorexia, sarcopenia, and high systemic levels of TNF-α, IL-1β, IL-6, and IL-18 can impair heart function, induce myocardial fibrosis and cardiomyocyte atrophy." (PMID 39200115, 2024). "Neutrophil gelatinase-associated lipocalin (NGAL), kidney injury molecule-1 (KIM-1), interleukin-18 (IL-18) and liver fatty acid-binding protein (L-FABP) have been suggested to be early markers of acute kidney injury, which effectiveness should be confirmed in studies." (PMID 32557377, 2020). "After 24 h, only serum levels of IL-18 were much higher in patients with CI-AKI than in those without acute kidney injury, however, this difference was on the verge of significance." (PMID 32557377, 2020). "The AUCs for diagnosis of AKI are greater than that for urinary biomarkers of acute kidney injury in the same cohort, namely, γ-glutamyltranspeptidase (GGT), alkaline phosphatase (AP), neutrophil-gelatinase-associated lipocalin (NGAL), kidney injury molecule (KIM-1), and interleukin (IL-18)." (PMID 24982893, 2014). "• Urinary interleukin-18 (IL-18) measured on arrival in the intensive care unit and at 24 hours postoperatively does not predict acute kidney injury in adult cardiac surgical patients." (PMID 18673539, 2008). "Biomarkers for postoperative renal failure after EVAR are extremely debated in the literature, with some having strong references (NGAL, cystatin C) and others having weaker data to support their use (retinol binding protein, IL-18, N-acetyle-b-D-glocosaminidase)." (PMID 35054350, 2022). "Inflammation underlies the pathogenesis of many renal diseases, including acute kidney injury (AKI) and chronic kidney disease (CKD), and the role of IL-18 in inflammation has been reported in many experimental animal models." (PMID 33732720, 2021). "In adults, early postoperative measurement of urinary IL-18 appears not to be valuable in identifying patients who develop acute kidney injury after cardiac surgery, but rather represents a nonspecific marker of cardiopulmonary bypass-associated systemic inflammation." (PMID 18673539, 2008). "It is important to note that the diagnostic performance of these biomarkers is not limited to DKD and can be influenced by other factors, such as infectious processes, which can affect molecules such as IL-18, NGAL, and calprotectin without necessarily indicating the presence of acute kidney injury." (PMID 37189380, 2023). "In recent months it has proved to be clear that a single biomarker would not suffice for the diagnosis of acute kidney injury, instead, it has been elaborated that a consortium of peptides such as KIM-1, NGAL, IL18 and IGFB7, TIMP-2 will be indicative for injuries of the nephron." (PMID 28545475, 2017).
systemic lupus erythematosus (80 papers, 2008 to 2025). An autoimmune multi-organ disease typically associated with vasculopathy and autoantibody production. "How mutated IL-18 and TNFα gene polymorphisms regulate the mRNA expression of IL-18 and TNFα and then be involved in lupus pathogenesis needs discussion." (PMID 38164134, 2023). "This study is a meta-analysis aimed at pooling reported data and clarifying the association between circulating level of interleukin-18 and systemic lupus erythematosus (SLE)." (PMID 33633218, 2021). "Various inflammatory cytokines, including interleukins (IL-6, IL-17, and IL-18), type I interferons, and tumor necrosis factor-α (TNFα) have been implicated in the pathogenesis of lupus." (PMID 33953971, 2021). "Collectively, findings from these clinical studies, and improvement of LN in the setting of IL-18 deficiency or blockade in a lupus-prone mouse model, suggest a pivotal role for IL-18 in the pathogenesis of renal SLE." (PMID 29930551, 2018). "Polymorphisms of the IL-18 gene have been shown to influence some chronic inflammatory diseases including diabetes, RA, systemic lupus erythematosus (SLE), and IBD." (PMID 30140708, 2018). "Genetically, single-nucleotide polymorphisms in IL18 gene are also related to the pathogenesis of lupus." (PMID 26690141, 2015). "Several studies point to a contribution of IL-18 to symptoms associated with human lupus and the lupus-like disease in mouse models." (PMID 26465326, 2015). "IL-18 contributes to the onset and severity of lupus indicating a critical pathogenic role of this cytokine." (PMID 24945254, 2014). "The stronger correlation between sFas and IL-18 in LN compared with mild lupus emphasizes the important pathogenic role of these two markers in kidney damage." (PMID 23577265, 2013). "Researchers have emphasized the pathogenic function of IL-18 and Fas/Fas ligand pathway in autoimmune-related diseases like lupus." (PMID 23577265, 2013). "The possible pathogenic role of IL-18 in lupus has been confirmed by the possibility of inducing nephritis and raised levels of pro-inflammatory cytokines in MRL/lp mice." (PMID 27713252, 2010). "A new putative IL18 gene variant was identified in systemic lupus erythematosus (SLE) patients." (PMID 30717382, 2019). "Notably, these high IL-18 levels correlate with impairments in vascular repair – in lupus, excess IL-18 is associated with endothelial progenitor cell dysfunction and hence may contribute directly to premature vascular damage." (PMID 41488670, 2025). "Future research must clarify IL-18’s role in renal cytokine networks to develop therapies targeting renal inflammation in systemic lupus erythematosus (SLE)." (PMID 41142814, 2025). "Activation of spinal microglial GPR109A suppresses p38 MAPK signaling and diminishes glutamatergic synaptic activity by decreasing IL-18 and IL-1β production in the dorsal horn of female lupus mice with chronic pain." (PMID 41511304, 2025). "Dysregulation of the IL-18/IL-18BP axis results in excessive bioactivity of free IL-18, a key mediator of inflammation in systemic lupus erythematosus (SLE) and lupus nephritis (LN)." (PMID 41142814, 2025). "Fli-1′s regulation of the IL-1β and IL-18 genes in lupus mice was further confirmed in the lung pericytes of Cecal ligation and puncture (CLP)-induced sepsis models." (PMID 40305194, 2025). "Previous studies have also investigated the clinical value of IL18 in various diseases and reported that IL18 elevated in IgA nephropathy, systemic lupus erythematosus, and fatal cardiovascular diseases." (PMID 39934489, 2025). "Elevated IL-18 levels in lupus patients correlate with the severity of oral lesions, underscoring its potential as a biomarker for disease monitoring." (PMID 40791585, 2025).
systemic lupus erythematosus (continued). "The activation of spinal GPR109A with MK1903 resulted in the attenuation of p38 MAPK activity and glutamatergic synaptic activity by suppressing the production of IL-18 and IL-1β in the spinal dorsal horn of lupus mice with chronic pain." (PMID 38612414, 2024). "This enhanced glutamatergic synaptic activity and the resulting chronic pain in lupus mice are attributed to the overproduction of proinflammatory cytokines (such as IL-1β and IL-18), CSF-1, and thrombin, as well as reduced AMPK activity in the same region." (PMID 38612414, 2024). "It has been reported that the activation of glial cells in the spinal dorsal horn of lupus mice experiencing chronic pain was accompanied by the increased production of IL-1β, IL-18, and cathepsin B." (PMID 38612414, 2024). "Activation of the microglial GPR109A receptor in the spinal dorsal horn attenuates glutamatergic synaptic activity and hypersensitivity in lupus mice by suppressing the overproduction of spinal IL-1β and IL-18." (PMID 38612414, 2024). "The heightened production of IL-18 in the spinal dorsal horn not only contributes to the genesis of chronic pain induced by lupus but also in cases resulting from nerve injury and bone cancer." (PMID 38612414, 2024). "There is also evidence of a correlation between ISG expression, IL-1β and IL-18 production, and the inflammasome in patients with autoimmune disorders associated with elevated levels of IFNs such as systemic lupus erythematosus (SLE) and juvenile dermatomyositis." (PMID 38527803, 2024). "The activation of microglial GPR109A receptors in the spinal cord mitigates thermal hyperalgesia in female lupus mice by suppressing the production of IL-1β and IL-18, as well as p38 MAPK (see Section 6.5 for details)." (PMID 38612414, 2024). "For example, a significant increase in IL-18 levels was found in the serum of patients with systemic lupus erythematosus, and its expression also correlated with the intensity of damage and renal activity in patients." (PMID 37859999, 2023). "DHA has increased the lifespan of and suppressed glomerulonephritis in NZB × NZW mice with systemic lupus erythematosus, possibly due to inhibition of IL-18 induction." (PMID 37511964, 2023). "For example, in systemic lupus erythematosus, biomarkers such as IL-18 and TNFα are preferred over CRP for disease monitoring." (PMID 37476185, 2023). "In MRL/lpr mice model, disease severity worsened when exogenous IL-18 was given whereas lupus was alleviated when mice were treated with anti-IL-1810." (PMID 33633218, 2021). "EGCG also inhibited NLRP3 inflammasome activation by reducing NLRP3 expression and production of active caspase-1, IL-1β, and IL-18 in NZB/W F1 lupus-prone mice." (PMID 33418975, 2021). "Imbalance of IL-18/IL-18BP in patients was reported in several diseases, such as hemophagocytic syndrome and systemic lupus erythematosus, but IL-18BP was only moderately elevated even under the active stage." (PMID 33922655, 2021). "Interest in IL-18 in systemic lupus erythematosus (SLE) has been mostly focused on its role as a type 1 T helper cell-driving cytokine." (PMID 33919154, 2021). "IL-18BP also acts to reduce IL-18 agonist activity and an imbalance of IL-18 and IL-18BP has been described in Wegener’s granulomatosis and systemic lupus erythematosus." (PMID 33643264, 2021). "Though not all changes were statistically significant, similar observations were made for TNF-α, IL-1α, IL-6, and IL-18, which are known for their roles in inflammation and lupus development." (PMID 32413078, 2020). "The results showed that the serum levels of IL-1β and IL-18 remarkably increased in lupus mice, while baicalein significantly inhibited the production of these cytokines." (PMID 31023362, 2019).
systemic lupus erythematosus (continued). "In Wegener’s granulomatosis and systemic lupus erythematosus, the serum levels of IL-18BP and IL-18 were high, but the level of IL-18BP was insufficient to neutralize IL-18 and the level of free IL-18 was higher than that of healthy individuals." (PMID 30717382, 2019). "In the MRL lpr/lpr murine lupus model, up-regulation of IL-18 expression is detected in all affected organs, including nephritic kidneys." (PMID 29422069, 2018). "IL-1β and IL-18 are two members that have been shown to play a role in murine lupus-like models, but their role in human SLE remains poorly understood." (PMID 29930551, 2018). "Multivariable associations of serum IL-18 in systemic lupus erythematosus (SLE)." (PMID 29930551, 2018). "Univariable associations of serum IL-18 in systemic lupus erythematosus (SLE)." (PMID 29930551, 2018). "Other diseases, such as systemic lupus erythematosus, inflammatory bowel disease, and autoimmune lymphoproliferative syndrome, also exhibit elevated serum IL-18 concentrations (20, –22)." (PMID 28225869, 2017). "CD69 expression on MAIT cells in patients with lupus positively correlated with plasma concentrations of IL-6, IL-18, and IFN-α." (PMID 28288675, 2017). "In this study, we generated MRLlpr mice, which develop a disease resembling systemic lupus erythematosus, genetically devoid of IL-18 expression." (PMID 26465326, 2015). "In a MRL/MP-lpr/lpr (MRL/1) mouse, a lupus murine model, elevated IL-18 was observed in the serum and organs, including the kidney." (PMID 26690141, 2015). "We conclude that in the systemic lupus erythematosus syndrom IL-18 is involved specifically in the renal pathogenesis." (PMID 26465326, 2015). "To continue our previous study, in this paper, we carefully examined the correlation between sFas and IL-18 serum concentrations in lupus nephritis compared with mild lupus." (PMID 23577265, 2013). "If one examines immunologically mediated diseases where IFNγ plays a pathological role such as Wegener’s granulomatosis and systemic lupus erythematosus, one must consider the level of free IL-18 compared to IL-18 bound to IL-18BP." (PMID 24115947, 2013). "In our previous study, we also demonstrated that sFas and IL-18 rise in correlation with disease activity in lupus." (PMID 23577265, 2013). "The results of this study were in line with our previous study, which revealed a strong positive correlation between serum levels of sFas and IL-18 in lupus and other studies that demonstrated the impressive action of IL-18 and sFas in LN." (PMID 23577265, 2013). "Our data are in contrast to the documented role of IL-18 signaling in spontaneous lupus-like immune complex glomerulonephritis of MRLlpr(Fas) mice." (PMID 22046355, 2011). "This fact should be taken into account when the results of two other studies are contemplated, in which a dysregulation of the IL-18/IL-18BP equilibrium in systemic lupus erythematosus (SLE) and Wegener's granulomatosis (WG) was reported." (PMID 20072626, 2010). "In the MRL/lpr lupus-prone mouse model, elevated IL-18 expression is detectable in the kidneys." (PMID 41142814, 2025). "Moreover, administering GDF-15 to lupus-prone mice led to a decrease in several proinflammatory cytokines, including IL-1β, IL-18, and IL-22, highlighting its role in modulating the immune response." (PMID 40722837, 2025). "IL-18 is recognized as a crucial cytokine that influences the severity of oral lesions in lupus." (PMID 40791585, 2025). "The P2X7 receptor is involved in systemic lupus erythematosus through the activation of the NLRP3 inflammasome and increased production of IL-1β and IL-18 by lupus patient-derived macrophages, thereby contributing to the cardiovascular, cutaneous, and renal manifestations of lupus." (PMID 41002432, 2025). "Therefore, enhanced TLR7 signaling in lupus mice likely amplifies neuronal activity and promotes spinal central sensitization by increasing the production and release of IL-1β and IL-18." (PMID 41511304, 2025).
systemic lupus erythematosus (continued). "describe a case of SLE and T-LGLL with levels of IL-18 correlating with lupus symptoms as well as the number of T-LGLs in serum suggesting IL-18 may activate T-LGLL." (PMID 35747794, 2022). "However, IL-18 administration by itself is unable to induce a lupus-like pathogenesis in MRL/Mp-Tnfrsf6+/+ mice." (PMID 26465326, 2015). "Decreased IL-18 gene expression observed here at wk 34 in kidneys of DFO-fed mice as compared to HOS- or CRN-fed mice therefore might be a factor in reduced lupus manifestations." (PMID 24945254, 2014). "The main question in the current study was whether the correlation between sFas and IL-18 in LN is stronger than that correlation in mild lupus." (PMID 23577265, 2013). "However, it is necessary to calculate the level of free IL-18 since IL-18BP is present in the circulation in health and disease in lupus, Wegener’s granulomatosis." (PMID 24115947, 2013). "Furthermore, in murine lupus models, IL-18 serum levels correlate with LN severity." (PMID 37261358, 2023). "Serum cytokines of IFN- α, IL-6, IL-8, IL-17, and IL-18 correlate with SLE disease severity measured by Systemic Lupus Erythematosus Disease Activity Index (SLEDAI)." (PMID 31842967, 2019). "Monotherapy of systemic lupus erythematosus (SLE) patients with chloroquine results in a decrease in serum levels of IL-6, IL-18, and TNF-α." (PMID 25348033, 2014). "Moreover, the abnormal activation of intracellular MAPK upon IL-18- stimulation may account for hyperactivity of peripheral lymphocytes in systemic lupus erythematosus (SLE)." (PMID 22867055, 2012). "IL-18 was also shown to induce the ex vivo release of IL-17 and IL-23 from lymphocytes of systemic lupus erythematosus (SLE) patients." (PMID 22229105, 2012). "Importantly, an imbalance between IL-18 and IL-18BP may actively contribute to lupus pathogenesis." (PMID 41357229, 2025). "It is important to note that IL-18 is a potent inducer of IFN-γ which can both skew the Th response towards a Th1 pattern and promote inflammation in lupus." (PMID 24945254, 2014). "One-sample Kolmogorov-Smirnov test was used to evaluate distribution of age, IL-18, sFas, C3, C4, ESR, anti-dsDNA, and 24-hour urine protein excretion parameters in three groups including all participants, severe lupus, and mild lupus separately." (PMID 23577265, 2013). "Although early reports demonstrated defective Th1 and excessive Th2 responses in lupus, recent data suggest that the levels of both Th1 (IFN-γ, IL-12, and IL-18) and Th2 (IL-4, and IL-10) cytokines are increased in the sera of lupus patients." (PMID 22761630, 2012). "Patch-clamp whole-cell recordings have shown that the bath perfusion of IL-18 antagonists (IL-18BP) attenuated the frequency but not the amplitude of miniature AMPA currents recorded from spinal slices obtained from lupus mice with chronic pain." (PMID 38612414, 2024). "In contrast to other inflammatory conditions, including RA, systemic lupus erythematosus (SLE), ankylosing spondylitis (AS), and psoriatic arthritis (PsA), the circulation amount of free IL-18 is higher in individuals with AOSD during both the active and inactive phases of the condition." (PMID 36361602, 2022). "In addition, it has been found that IL-18 is upregulated in systemic lupus erythematosus (SLE) serum and gout and may play an important role in proinflammatory cytokine production." (PMID 34055402, 2021). "Elevated levels of IL-18 were observed in kidney biopsies, as well as in serum of LN patients, when compared with lupus patients without nephritis." (PMID 33919154, 2021). "In our model, IL-18 does not affect the lupus-like pathogenesis generally, but specifically some parameters of affected end-organs, i. e. the kidneys." (PMID 26465326, 2015). "The role of IL-18 in the pathogenesis of systemic lupus erythematosus is still not definitively solved." (PMID 26465326, 2015).
systemic lupus erythematosus (continued). "In brief, the current study illustrated that serum values of sFas and IL-18 are significantly higher in lupus patients with proteinuria compared with patients without proteinuria." (PMID 23577265, 2013). "Furthermore, the pharmacological activation of spinal GPR109A receptors in microglia in lupus mice suppresses chronic pain by inhibiting p38 MAPK activity and the production of both IL-1β and IL-18, as well as reducing glutamatergic synaptic activity in the spinal dorsal horn." (PMID 38612414, 2024). "High levels of serum IL-18 levels were reported in patients with systemic juvenile idiopathic arthritis (s-JIA) and its adult homolog adult Still’s disease (AOSD), as well as various other inflammatory diseases including systemic lupus erythematosus and Crohn’s disease." (PMID 36211331, 2022). "One study showed that EGCG was able to prevent the development of LN in NZB/WF1 lupus-prone mice due to inactivation of the Nrf2 antioxidant pathway, which resulted in renal NLRP3 inflammasome inactivation with less amounts of IL-1β and IL-18 in kidney lysates." (PMID 34830358, 2021). "In patients with systemic lupus erythematosus (SLE), MAIT cells can be activated by IFN-α, IL-15, and IL-12 plus IL-18 in the absence of exogenous antigens." (PMID 29176983, 2017).